RN7SKP164 (RN7SK pseudogene 164)
Gene: Miscellaneous RNA gene on chromosome 2 (76,595,413 to 76,595,678, reverse strand). Ensembl gene ENSG00000251947.
Homologues: Orthologues: chimpanzee 7SK (84% identical). Paralogues in human: RN7SKP79 (58% identical), RN7SKP127 (57% identical), RN7SKP180 (57% identical), RN7SKP124 (56% identical), RN7SKP153 (56% identical), RN7SKP170 (56% identical), RN7SKP240 (56% identical), RN7SKP250 (56% identical), RN7SKP150 (56% identical), RN7SKP194 (56% identical), RN7SKP268 (56% identical), RN7SKP33 (56% identical), and 284 more.